LGR5 (leucine rich repeat containing G protein-coupled receptor 5)
Diseases named in the same sentence as LGR5 in open-access papers (continued):
Sharing a sentence is not in itself a finding about the gene and the disease.
cancer (continued). "Moreover, higher Lgr5 expression was statistically significantly related to vascular invasion in examined cancer tissue samples (p = 0.027)." (PMID 32671503, 2020). "Overexpression of LGR5 increases drug resistance and cancer stemness in both brain tumors and CRC." (PMID 33489917, 2020). "The presence of Lgr5 might be an unfavorable prognostic factor, and its high level in cancer tissue is related to an aggressive course." (PMID 32671503, 2020). "While the role of nuclear Lgr5 in the gastric epithelium and in cancer cells remains largely unexplored, it is worth noting that several studies examining Lgr5(+) cells based their identification of Lgr5(+) cells based on LGR5 mRNA expression and/or LGR5-driven reporters (ex." (PMID 32894084, 2020). "Furthermore, the expression of LGR-5 protein, a specific NB marker for cancer stem cells, in all PDOs suggests the preservation of cancer stem cells subpopulation." (PMID 31638925, 2019). "We observed the cancer stem cell marker LGR-5 expressed in all PDOs." (PMID 31638925, 2019). "Furthermore, in our study the mRNA level of the LGR5 transcript variants were positively correlated with the mRNA level of CTGF, P4HA1, and IGF2, as all of these genes are linked to metastasis in cancer." (PMID 30770730, 2019). "Recently, researches have introduced Lgr5 as a potential adult cancer stem cell marker." (PMID 31814939, 2019). "Simultaneously, combination of therapeutics targeting both Lgr5+ and Lgr5− cancer cells may deserve further consideration considering the plasticity of cancer cells." (PMID 31358061, 2019). "Moreover, in CRC patients, the expression of Lgr5, the cancer stem cell marker, was positively correlated with PKM expression." (PMID 30996297, 2019). "Interestingly, Lgr5, a cell surface-expressed Wnt target gene, has been demonstrated as a functional biomarker of cancer stem cells, contributing to cancer stem cell proliferation and self-renewal through the regulation of Wnt/β-catenin signaling pathway." (PMID 31358061, 2019). "KRT19+/Lgr5− cells may be cancer-initiating and radioresistant, making them functionally distinct from the radiosensitive Lgr5+ ISC population." (PMID 30999572, 2019). "However, upon ablation of LGR5+ cells, differentiated KRT20+ cancer cells can revert to LGR5+ cells and drive cancer regrowth." (PMID 31097693, 2019). "Aberrant increased expression of Lgr5 may represent one of the most common molecular alterations in some human cancers, leading to long-term potentiation of canonical Wnt/β-catenin signaling." (PMID 31358061, 2019). "Recent studies have explored the function of LGR5 in various cancer types." (PMID 29471794, 2018). "Moreover, increasing evidence shows that Lgr5 is involved in Wnt/β-catenin pathway in the regulation of cancer stem cells." (PMID 28404917, 2017). "Furthermore, proliferating activity varied among Lgr5+ tumorigenic cells as rapidly proliferating cells behaved as cancer-stem-like cells, which clonally expanded." (PMID 28176811, 2017). "ALDH-1, CD133, CD44, Lgr-5, and Msi-1 are markers for the acquisition of cancer stemness." (PMID 28862656, 2017). "We asked whether loss of LGR5 affects cytoskeletal structures of crypt stem cells given the effect of LGR5 on the actin cytoskeleton in cancer cell lines." (PMID 28739799, 2017). "However, the exact roles and mechanisms of LGR5 in normal adult stem cells and cancer cells remain poorly defined." (PMID 28739799, 2017). "This positive correlation between gankyrin and Lgr5 or Bmi1 suggests that gankyrin might be related with cancer stem cell behavior in IBD patients." (PMID 28160571, 2017). "We found that metformin reduced the RNA expression of two colorectal CSC markers involved in Wnt signalling, CD44 and LGR5, thus confirming that it may affect cancer cells with “stem” characteristics." (PMID 29167573, 2017).
cancer (continued). "As we already established LGR5 as a predictive marker of putative cancer stem cells within the gastric mucosa, we now show that the expression of its antagonist Troy might improve the patient's outcome by inducing differentiation." (PMID 28881583, 2017). "We recently reported the importance of Lgr5-positive CRC cells in cancer growth." (PMID 27835894, 2016). "The Lgr5+/CXCR4+ cancer cells were generated by co-transduction with both AAVs." (PMID 27835894, 2016). "Nuclear IKKα could directly bind to the promoters of inflammation factors and LGR5, a stem cell marker, in turn, upregulating LGR5 expression through activation of STAT3 signaling pathway during cancer progression." (PMID 27049829, 2016). "Hypermethylation of lgr5 results in cancer stem cell differentiation." (PMID 26599100, 2015). "Lgr5 is specifically expressed on cancer stem cells (CSCs) and is known to amplify the effect of Wnt/β-catenin signaling by working as a receptor for R-spondins (RSPO), which are well established and influential agonists of the Wnt pathway, and known key drivers of oncogenesis." (PMID 26697427, 2015). "Therefore, the expression of lgr5 in these cancer cell lines well correlated with the methylation status of the promoter CpG islands, supporting DNA methylation as a mechanism for regulating lgr5 level." (PMID 26599100, 2015). "In search of cancer stem cells markers, Barker and Clevers in 2000 uncovered the dogmatic existence of adult stem cell marker Lgr5 also known as G-protein coupled receptor (GPR49) (chromosome 12; position 12q22–q23)." (PMID 26697427, 2015). "In recent years Lgr5 has been reported to promote both growth and survival and is over expressed in several types of cancer including colorectal cancers, where heightened expression was restricted to actively proliferating cells, Ovarian cancer, and Thyroid Cancer." (PMID 26697427, 2015). "We were able to examine LGR5 expression in 18 cases of adenocarcinoma, and consistent with the findings of Merlos-Suarez and colleagues, we report that in the majority of established carcinomas with a glandular structure, compartmentalization of LGR5 and KRT20 is present." (PMID 25728748, 2015). "Leucine-rich repeat-containing G protein-coupled receptor 5 (LGR5), a seven transmembrane receptor known as a potential stem cell marker for intestinal crypts and hair follicles, has recently been found to be overexpressed in some types of human cancers." (PMID 25193857, 2014). "The importance of stem cell markers in identifying cancer stem cells, including Frizzled-4, Lgr5, and CD133 have previously been demonstrated, and here our data suggest that their expressions may be dependent on common precursor protein Sox2." (PMID 25380620, 2014). "Indeed aberrant gene transcription of some markers associated with carcinogenesis, NOX1, LGR5, MS4A12, reveal greatest deviation from that of normal tissue in the adenomatous polyps prior to development of carcinoma." (PMID 25423035, 2014). "Lineage tracing indicates that Lgr5+ cells may not only be the cells responsible for the origin of tumors; they may also be the so-called cancer stem cells." (PMID 24340024, 2013). "In particular, LGR5 expression was increased in putative cancer stem cells." (PMID 23596566, 2013). "Likewise, the initiation and proliferation of intestinal adenomas and carcinomas is driven by Lgr5+ stem cells." (PMID 23596566, 2013). "Nonetheless, whether LGR5 up-regulation itself contributes to cancer progression or simply is a surrogate marker, necessitates further investigations." (PMID 22530031, 2012). "Interestingly, LgR5 was identified to be expressed on crypt stem cells (precursor cells) as well as lesions which had progressed to cancer." (PMID 21345220, 2011). "According to our hypothesis, that the intestinal stem cell marker LgR5 might also be suited to identify cancer stem cells, these might be the actively cycling Barrett (cancer) stem cells." (PMID 21345220, 2011).
cancer (continued). "Furthermore, targeting LGR5 (+) stem cells in a specific phase of cancer or exploring effective strategies for targeting CSCs, such as TME combination targeting, could be the hotspots in the near future." (PMID 41194856, 2025). "Additionally, αSMA+ fibroblasts reduce LGR5 (+) cancer stem cells and inhibit CRC progression." (PMID 41194856, 2025). "Therefore, targeted drug delivery systems or genome editing strategies directed at LGR5-positive cancer cells may provide novel anticancer approaches." (PMID 41194856, 2025). "Early interim data from phase 2 clinical studies demonstrate encouraging clinical activity in r/m HNSCC that is substantially superior to historical results for standard approved therapies and may reflect a more effective treatment of the stem-cell-like LGR5+ cells within the cancer." (PMID 40427162, 2025). "However, LGR5 (+) stem cells are replenished with LGR5 (+) cells, leading to cancer metastasis." (PMID 41194856, 2025). "However, LGR5 has also been described as a cancer stem cell marker for various malignancies." (PMID 39769183, 2024). "LGR5 also regulates cell–cell adhesion, which may play an important role in cancer cell metastasis." (PMID 39065640, 2024). "Thus, we cultured LGR5+ cells alone or co‐cultured with cancer‐associated fibroblasts, under the situation with/without DT supplement to ablate LGR5‐expressing cells." (PMID 37578396, 2023). "ob-aT bASCs exhibited an increased ability to stimulate cancer stemness in highly malignant MDA-MB-231 cells by enhancing the gene expression of pluripotency and CSC associated genes such as ALDH1H1, ALDH2, c-MYC, CD34, LGR5, CXCR4, SOX2 and OCT4, fueling further their malignant potential." (PMID 36710348, 2023). "Along with these findings, our results of exceptional LGR5 expression in the secretory cells may support the notion that secretory cells harbor a group of stem cell populations in the fallopian tube, acting as cells of origin for this cancer." (PMID 35778589, 2022). "Additionally, CtBPs may directly coactivate TCF4/LEF at key target promoters (c-Myc, LGR5) to promote cancer stem cell self-renewal." (PMID 35299743, 2022). "Thus, the high level of LGR5 in CCAOs that colonize the lymph node suggests that there is a pool of cancer stem cell-like cells present which could be responsible for migration from the lymph node to the lungs." (PMID 36741736, 2022). "Furthermore, Lgr5 itself could have a role in EMT-like phenotype retention since may exert opposing functions during the progression of different cancer types." (PMID 35854363, 2022). "Finally, in cancer stem cells (CSCs) of tumorspheres from SW620, the combined treatment of AHCC and ETAS caused a significant reduction in the gene expression of LGR5 and Notch1, opening new perspectives for the testing of these compounds in association with conventional chemotherapy." (PMID 34959725, 2021). "However, there is no comparison between LGR5 expression and prognosis in PD-AC using RNAscope, and the association between high LGR5 expression and poor prognosis in poorly differentiated cancer is a new finding." (PMID 33676447, 2021). "The identification of Lgr5 as a reliable marker of normal intestinal epithelial stem cells, together with strategies to trace cell lineages within tumors and the possibility to selectively ablate these cells, have proven the relevance of Lgr5+ cells for cancer progression." (PMID 33671641, 2021). "Lgr5, a cell surface-expressed Wnt target gene and a receptor for the Wnt‐agonistic R‐spondins (RSPOs), is a novel bonafide marker of adult organ stem cells as well as a functional biomarker of CSCs, contributing to cancer stemness traits through the regulation of Wnt/β-catenin signaling pathway." (PMID 34453639, 2021).
cancer (continued). "Subsequent sorting of cells from the xenograft tumors showed that Lgr5-eGFP+ cells from xenografts exhibited a significantly higher clonogenic potential than Lgr5-eGFP− in vitro, and were more tumorigenic upon transplantation in vivo, mimicking the conventional approach to cancer stemness." (PMID 33671641, 2021). "Therefore, the poor prognosis of patients with high LGR5 expression may be related to the histological features of poorly differentiated cancer represented by enhanced migration ability, EMT-related protein expression, and LGR5 expression." (PMID 33676447, 2021). "Therefore, it is reasonable to speculate that the appearance of LGR5-positive cells in the DCIS myoepithelium can be attributed to them sensing the pressure of an increasing number of cancer cells as a signal of tissue injury." (PMID 34493772, 2021). "However, whether Lgr5 expressing cells in acid-secreting corpus region are cancer cell origin is to be debatable." (PMID 33043003, 2020). "Our study shows for the first time that a revival stem cell signature strongly correlates with chemoresistance in PDCOs and suggests that the process of re-population of LGR5+ cells observed in normal tissue, may also operate with a similar mechanism in human cancer." (PMID 31906589, 2020). "Moreover, Lgr5− cancer cells might have a slightly higher displacement and velocity than Lgr5+ CSCs." (PMID 32169167, 2020). "Therefore, we tested whether hypoxic condition would promote LETM1 and cancer stemness gene LGR5 expression in NSCLC cells." (PMID 31500591, 2019). "Therefore, Lgr5 may exert complicated or even opposing functions during the progression of different cancer types." (PMID 31358061, 2019). "Thus, NF-κB signaling-induced abnormal immune response during cancer development may be another important stimulating factor of Lgr5 expression." (PMID 31358061, 2019). "However, until now, the prognostic significance of Lgr5 in cancer still remains controversial." (PMID 31358061, 2019). "In addition, the population of Lgr5+ CSC was elevated in cancer tissues from PKM2ΔLgr5-Tx mice." (PMID 30996297, 2019). "Thus, a combined therapy targeting both Lgr5+ and Lgr5− cancer populations may deserve further consideration." (PMID 31358061, 2019). "Therefore, increasing evidence suggest that targeted suppression of Lgr5 in some certain cancer types may represent potential therapeutic approaches for treating cancer." (PMID 31358061, 2019). "Lgr5 may exert multiple or even different functions between different cancer types." (PMID 31358061, 2019). "Furthermore, a combined therapy targeting both Lgr5+ and Lgr5− cancer cells may desire further consideration and experimental validation." (PMID 31358061, 2019). "Therefore, targeted therapeutic modulation of Lgr5+ cancer cell population by targeting Wnt/β-catenin signaling through targeted drug delivery system or targeted genome editing might be promising for potential novel anti-cancer treatments." (PMID 31358061, 2019). "RSPO2 might also enrich CSCs by regulating Lgr5 expression in cancer cells." (PMID 28404917, 2017). "These suggest that LGR5 may enhance cancer stemness properties in HCC." (PMID 28455968, 2017). "Thus, induction of apoptosis in DNA-damaged Lgr5+ stem cells is likely to be a useful marker for successful cancer prevention, and may hold promise for identifying novel and improved cancer-chemopreventive agents." (PMID 27831561, 2016). "The higher expression of LGR5 in LI organoids could mean the presence of cells with higher resistance to damage, DNA repair and growth advantage that, if transformed, could confer resistance to cancer cells." (PMID 25751518, 2015). "In addition, we also examined the lgr5 expression by IHC.Lgr5 negative expression was associated with lgr5 methylation in the same cancer patients tissue by MSP." (PMID 26599100, 2015). "Thus, there is compelling evidence that LGR5 contributes to cancer initiation and progression." (PMID 24172981, 2014).
cancer (continued). "LgR5 signalling may therefore play a biological role in potentially cancer-initiating BE cells." (PMID 21345220, 2011). "The transmembrane glycoproteins cluster of differentiation 133 (CD133), aldehyde dehydrogenase 1 (ALDH1), and leucine-rich repeat-containing G protein-coupled receptor 5 (LGR5) are CSC markers in CRC 7, 8 and other various cancers 9-11." (PMID 41438576, 2026). "Notable was also the expression of TBX3 in the LGR5+ cell compartment, indicating that TBX3 is likely to function in intestinal epithelial stem cells or cancer stem cells originating from this tissue." (PMID 40343989, 2025). "Upregulated CASC15 expression in CRC cells promoted LGR5 expression by inhibiting miR-4310 expression, a state that activates the Wnt/β-catenin signaling pathway in CRC to promote cancer cell metastasis, migration." (PMID 40746360, 2025). "The activation of the Wnt/β-catenin pathway by CagA+ H. pylori in cancer cells promotes the expression of key cancer stem cell markers, which encompass CD44, Lgr5, Oct4, Nanog, and c-myc." (PMID 40497987, 2025). "We therefore tested culturing organoids in 2D on collagen I-coated plates, which induced (i)REC marker genes, while repressing the stem cell markers LGR5 and DACH1, indicative of cancer cells transitioning into (i)REC states." (PMID 40393458, 2025). "We also confirmed that YTHDF1 promoted CD133 and LGR5 expression in CSCs, xenograft models, and CSC-specific Ythdf1 knock-in/knockout mice, suggesting that YTHDF1 directly boosts cancer stemness properties." (PMID 41423446, 2025). "TGF-β1 increased LGR5 and β-catenin expression via the TGF-β1 signaling pathway, which proves that LGR5 plays an important role in cancer immunosuppressive microenvironment mediated by Tregs and TGF-β1." (PMID 41194856, 2025). "We describe the development of α-LGR5 as a therapeutic antibody, and its functional validation in targeting LGR5+ CRC and pre-B-ALL cells as an ADC and by directing cytotoxic immune cancer cell killing in the BiTE and CAR modalities." (PMID 39169164, 2024). "The low sensitivity of LGR5 + cells to VTD can be due to their plasticity and ability to convert to other stem cells, which are observed with other anti-cancer drugs in CRC." (PMID 39502780, 2024). "CBLL1 silencing was confirmed at the mRNA level, and mRNA downregulation of other known stem cell markers including LGR5, NANOG and c-MYC was also detected in sh-CBLL1 HT29 cancer stem cell tumourspheres compared to sh-control tumourspheres." (PMID 38339195, 2024). "Next, we analyzed RNA-seq data of 24 NB cell lines in the Cancer Cell Line Encyclopedia (CCLE) database and found that LGR5 expression was relatively high in about half of the cell lines whereas LGR4 was expressed at lower levels in nearly all the cell lines." (PMID 39065640, 2024). "This increase in cancer stem cell biomarkers was confirmed at the protein level, as observed in cancer stem cell tumourspheres for Hakai (CBLL1), Lgr5 and Nanog compared to protein expression in monolayer cultures." (PMID 38339195, 2024). "We evaluated the mRNA levels of typical cancer stem markers, CD44, LGR5, SOX2, and TROY, using qRT-PCR." (PMID 38669046, 2024). "Previous studies have established high LGR5 transcript levels in CRC and some other cancers raising the possibility of using α-LGR5 as a cancer biomarker or developing immune-based strategies for therapeutic targeting." (PMID 39169164, 2024). "LGR5 is a WNT target gene that regulates self-renewal capacity and is widely used as a biomarker of CSCs in different types of cancer, including CRC." (PMID 38339195, 2024). "Expression of ALDH1A1, ALPL, ITGA6, CD44, PROM1 (CD133), LGR5, and YAP1 upregulated in the E2 and E3 phenotypes was consistent with cancer hallmarks including cell plasticity, self-renewal, and drug-tolerant persistence." (PMID 38915538, 2024). "HRCA showed remarkably higher expression levels of intestinal stem cell markers (LGR5, OLFM4) and cancer stem cell markers (c-Myc, CD166)." (PMID 37667332, 2023).